RBMY1B (RNA binding motif protein Y-linked family 1 member B)
Description:
RNA-binding protein which may be involved in spermatogenesis. Required for sperm development, possibly by participating in pre-mRNA splicing in the testis.
Tractability: No criterion of Open Targets' tractability assessment is met for any kind of drug.
Gene: Protein-coding gene on chromosome Y (21,511,338 to 21,525,786, forward strand). Ensembl gene ENSG00000242875.
Subcellular location: Nucleus
Subcellular location (Human Protein Atlas): Nucleoplasm; Nucleoli
Gene Ontology:
Molecular function: RNA binding; nucleic acid binding
Biological process: male gonad development; mRNA splicing, via spliceosome; spermatogenesis
Cellular component: nucleus; spliceosomal complex
Homologues: Orthologues: rat Rbmy1j (35% identical), macaque RBMY (34% identical), mouse Rbmyf9 (32% identical), mouse Rbmyf2 (32% identical), mouse Rbmyf3 (32% identical), mouse Rbmy (32% identical), mouse Rbmyf1 (32% identical), mouse Rbmyf5 (32% identical), mouse Rbmyf6 (32% identical), mouse Rbmyf7 (32% identical), mouse Rbmyf8 (32% identical), mouse Rbmyf4 (17% identical). Paralogues in human: RBMY1D (99% identical), RBMY1A1 (99% identical), RBMY1E (99% identical), RBMY1F (99% identical), RBMY1J (99% identical), RBMX (48% identical), RBMXL1 (46% identical), RBMXL2 (38% identical), RBMXL3 (32% identical), CIRBP (17% identical), RBM3 (14% identical), MSI1 (14% identical), and 24 more.
Diseases named in the same sentence as RBMY1B in open-access papers:
RBMY1B is named in the same sentence as 5 diseases in open-access papers, as found by Europe PMC text mining. Sharing a sentence is not in itself a finding about the gene and the disease. The quoted sentences say what the papers report.
cryptorchidism (1 paper, 2019). The failure of one or both testes of a male fetus to descend from the abdomen into the scrotum during the late part of pregnancy. "Our findings implicate Y-chromosomal genes, including USP9Y, UTY, TXLNGY, RBMY1B, RBMY1E, RBMY1J and TSPY4, some of which are known to be important for spermatogenesis, in the curative hormonal treatment of cryptorchidism-induced infertility." (PMID 31171972, 2019).
hepatocellular carcinoma (1 paper, 2017). A malignant tumor that arises from hepatocytes. "This study provides the first evidence of the expression of Y-linked lincRNA transcripts such as lnc-KDM5D-4:1, lnc-ZFY-1:1, lnc-ZFY-2:1, lnc-RBMY1B-1:1, lnc-RBMY1B-1:4, lnc-USP9Y-1:4, and lnc-HSFY2-3:6 in human hepatocellular carcinoma (HCC)." (PMID 29196750, 2017).
seminoma (1 paper, 2025). A radiosensitive malignant germ cell tumor found in the testis (especially undescended), and extragonadal sites (anterior mediastinum and pineal gland). "Additionally, focal deletions targeting the RBMY gene family (RBMY1A1, RBMY1B, RBMY1D)—male germ cell–specific RNA-binding proteins—were significantly enriched in seminomas (26.6% vs. 12.8% in non-seminomas; P = 0.0078)." (PMID 40568177, 2025).
RBMY1B also shares sentences with these, for which no sentence is quoted: Azoospermia (1 paper); Infertility (1).